NFE2L2 (NFE2 like bZIP transcription factor 2)
Diseases named in the same sentence as NFE2L2 in open-access papers (continued):
Sharing a sentence is not in itself a finding about the gene and the disease.
lung squamous cell carcinoma (22 papers, 2012 to 2024). "KEAP1/NFE2L2 had higher mutation frequency in lung squamous cell carcinoma (OAK/POPLAR, P = 0.05; OAK, P = 0.044; POPLAR, P = 0.069)." (PMID 34381706, 2021). "We also found NFE2L2 mutation which is frequently altered in lung squamous cell carcinoma and recently identified in TC as fusion driver." (PMID 31235699, 2019). "To gauge the utility of the method in predicting GOF mutations on a known proto-oncogene, we applied our method to mutations in NFE2L2 in lung squamous cell carcinoma." (PMID 22962493, 2012). "Also, we observed the activation of the NRE2 pathway in NFE2L2-mutated PDX samples in squamous cell lung cancer (LUSC), suggesting that PDXs may be suitable for studying key oncogenic pathways and corresponding drug responses." (PMID 34429404, 2021). "NFE2L2 is most frequently mutated in lung squamous cell carcinoma (LUSC), the same cancer type where ELMER detected NFE2L2 alterations." (PMID 25994056, 2015). "Additionally, in ten patients with lung squamous cell carcinoma, we identified mutations in KEAP1/NFE2L2 that influenced the expression of target genes in vivo and in vitro." (PMID 32629428, 2020). "In a lung cancer study, samples were taken from 178 lung squamous cell carcinomas (SqCCs) and, apart from 53BP1, most mutations were found in three genes associated with the Nrf2–ARE pathway, NFE2L2 (the gene name of Nrf2), Keap1, and Cul3 (the gene name of Cullin 3)." (PMID 27047795, 2016). "For NFE2L2 in lung squamous cell carcinoma, while the APSiC rank for the LK2 cells with the gain-of-function p.E79K mutation was < 0.001, the APSiC rank for EBC1 with the rarer p.D77V mutation was 0.83, suggesting that p.D77V may not critical to the survival of the EBC1 cells." (PMID 34313788, 2021). "ΔNp63α (TP63) mRNA levels positively correlated with NRF2 (NFE2L2) mRNA levels in ESCA and lung squamous cell carcinoma (LUSC)." (PMID 39500864, 2024).
ovarian carcinoma (21 papers, 2016 to 2026). A malignant neoplasm originating from the surface ovarian epithelium. "An overexpression of NFE2L2 has been shown to be associated with cisplatin resistance in bladder and ovarian carcinoma." (PMID 30029672, 2018). "To investigate the NRF2 gene expression pattern in clinical sample, transcriptomics data were extracted from TCGA database and we found that NFE2L2 expression was significantly upregulated in ovarian cancer." (PMID 38396022, 2024). "We show that an inhibition of this pathway either by NFE2L2 silencing or direct AKR1C1/2 inhibition by MPA resensitizes ovarian cancer cells to CTX and results in reduced viability, proliferation, and an increased apoptosis rate." (PMID 35115586, 2022). "Conversely, in human ovarian cancer cells, increased DNA methylation on the NFE2L2 promoter by the combined administration of trastuzumab and pertuzumab inhibited the expression of NRF2 and weakened its antioxidant function to perform an anti-cancer effect." (PMID 34248833, 2021). "Some can be used as potential therapeutic targets; for example, NFE2L2 can be used as a therapeutic target for glioblastoma, and upregulation of miR-383-5p can suppress proliferation and enhance chemosensitivity in ovarian cancer cells." (PMID 32915799, 2020). "NFE2L2 was found to be highly expressed in the ovarian cancer cell lines OVCAR3, UWB1.289, and TOV112D." (PMID 30597961, 2018). "Conversely, the combined therapeutics of trastuzumab and pertuzumab promoted DNA methylation on the Nfe2l2 promoter in human ovarian cancer cells, weakening the expression of Nrf2 and attenuating its antioxidant capacity, thereby achieving an anticancer effect." (PMID 36185600, 2022). "However, contradictory evidence exists; for instance, other studies have suggested that NFE2L2 induces cisplatin resistance by suppressing the iron export gene SLC40A1 in ovarian cancer cells, indicating the presence of unknown feedback mechanisms." (PMID 39534872, 2024). "In addition, ovarian cancer cells with high NFE2L2/NRF2 expression have been found to increase sensitivity to the ferroptosis inducer.This demonstrates that NRF2 is an important treatment target for ovarian cancer and plays a role in a variety of regulatory pathways." (PMID 39192972, 2024). "Finally, we explored whether factors such as ATF4, GPX4, GSS, KEAP1, NFE2 like BZIP transcription factor 2 (NEF2L2), SLC7A11, SQSTM1, ATG3, ATG4D, and ATG5 have potential as non-invasive diagnostic markers for ovarian cancer." (PMID 37215446, 2023). "In contrast to HNC cells, NFE2L2 downregulates NCOA4 mRNA and protein levels in ovarian cancer cells, both basally and in ferroptosis-inducing conditions." (PMID 39025451, 2024). "Although SYVN1 mediates erastin-induced ferroptosis in ovarian cancer cells by facilitating ubiquitination-dependent degradation of SLC7A11, direct evidence for SYVN1-dependent NFE2L2 degradation during ferroptosis remains limited." (PMID 39534872, 2024). "While layered and complex, NFE2L2 ultimately decreases the LIP and ferroptosis sensitivity in ovarian cancer cells." (PMID 39025451, 2024). "The results of multiple gene correlation analyses indicated that there was a significant linear relationship (positive correlation) between the expression of ATF4 in ovarian cancer tissue and the expression levels of GPX4, GSS, KEAP1, NFE2L2, SLC7A11, ATG3, ATG4D, and ATG5." (PMID 37215446, 2023).
Hyperglycemia (20 papers, 2013 to 2026). An increased concentration of glucose in the blood. "Hyperglycemia induced a downregulation of NFE2L2 (p = 0.19) in HUVEC whereas it upregulated NFE2L2 expression in HMVEC (p = 0.06)." (PMID 24093550, 2013). "Adipocyte-specific Nfe2l2-KO mice with a leptin-deficient ob/ob background (a model with an extremely positive energy balance) led to reduced WAT mass but with severe metabolic syndrome and serious insulin resistance, hyperglycemia, and hypertriglyceridemia." (PMID 35204118, 2022). "Not much detail is available in literature for hyperglycemia-induced gene expression of NFE2L2, TXNRD1, TXNRD2 and PRDX1 in HUVEC." (PMID 24093550, 2013).
depression (19 papers, 2018 to 2026). "Furthermore, NFE2L2 gene knockout increases susceptibility to depression." (PMID 33935736, 2021). "In the LPS and chronic unpredictable mild stress-induced depression models, NFE2L2 signals were found to play key roles." (PMID 33935736, 2021). "Based on these findings, we hypothesize that long-term olfactory absence results in chronic stress and suppression of the NFE2L2 signaling pathway, which leads to the development of depression." (PMID 33935736, 2021). "Overall, our study verified that during states of excessive oxidative stress, the PIK3CA/AKT1/NFE2L2/KEAP1 and PIK3CA/AKT1/BDNF/NTRK2 signaling pathways are suppressed, which induced OB rats to exhibit phenotypic behaviors of depression." (PMID 33935736, 2021). "Although determining the underlying mechanisms requires further investigation, our research highlights that NFE2L2 antioxidant signaling is important in depression and raises the possibility that the Chinese herbal compound, XYW, has promise as an effective treatment for depression." (PMID 33935736, 2021).
glioblastoma (19 papers, 2017 to 2025). The most malignant astrocytic tumor (WHO grade IV). "NFE2L2 is the gene that encodes Nrf2 and it is basally more expressed in Hs766T than in the rest of pancreatic and colorectal carcinoma and glioblastoma cell lines." (PMID 33198289, 2020). "We measured NFE2L2 expression in glioblastoma cells that either overexpressed SELH or had SELH expression silenced." (PMID 35387667, 2022). "On the other hand, colorectal carcinoma patients presented a lower NFE2L2 expression with respect to the healthy tissue, while glioblastoma patients have a higher expression in comparison with healthy brain tissue samples." (PMID 33540681, 2021). "The NFE2L2 expression in pancreatic carcinoma, colorectal carcinoma, and glioblastoma cell lines was between 29%–73.7% with respect to the observed in Hs766T." (PMID 33540681, 2021). "With respect to NFE2L2, 10% of patients with pancreatic carcinoma, 60% of patients with colorectal carcinoma and 50% glioblastoma biopsies have high expression levels." (PMID 33540681, 2021). "In the glioblastoma cell lines, the NFE2L2 expression levels ranged between 30%–73.7% with respect to the observed in Hs766T." (PMID 33540681, 2021). "We are taking these data in consideration and increasing our glioblastoma patients’ samples and primary cultures in order to probe a cause–effect relationship between CLytA-DAAO activity and NFE2L2 expression in glioblastoma." (PMID 33540681, 2021). "Additionally, NFE2L2 expression positively correlated with malignancy, with the glioblastoma cell line T98G showing significantly higher NFE2L2 levels than the neuroglioma cell line H4." (PMID 38819225, 2024). "Likewise, in T98G glioblastoma cells, which exhibit high basal NFE2L2 expression, NFE2L2 appears to increase ferroptosis sensitivity." (PMID 39025451, 2024). "NFE2L2 is involved in mediating TMZ glioblastoma resistance via MMP-2." (PMID 36231068, 2022). "Certainly, glioblastoma patients showed higher expression of NFE2L2 with respect to normal tissue." (PMID 33540681, 2021). "However, NFE2L2 expression has to be taken in consideration, especially in glioblastoma patients." (PMID 33540681, 2021). "Survival analysis performed with UALCAN showed that a high NFE2L2 expression in pancreatic carcinoma patients has a correlation with poor prognosis (p-value: 0.023), while in colorectal carcinoma and glioblastoma patients, no significant changes were observed in survival analysis (data not shown)." (PMID 33540681, 2021). "Regarding NFE2L2, CLytA-DAAO treatment would not be a problem either in pancreatic or colorectal carcinoma, however, in a percentage of glioblastoma patients, the expression level of these genes suggests a putative resistance to CLytA-DAAO treatment." (PMID 33540681, 2021).
COVID-19 (18 papers, 2021 to 2025). A disease caused by infection with severe acute respiratory syndrome coronavirus 2. "This increased expression suggests a pivotal role of NFE2L2 in the heightened immune response seen in severe COVID-19 cases, likely as a compensatory mechanism to counteract elevated oxidative stress." (PMID 39928675, 2025). "This suggests that NFE2L2 plays a crucial role in macrophage function and the inflammatory response during severe COVID-19." (PMID 39928675, 2025). "The upregulation of genes involved in hypoxia (HIF1α) and metabolic adaptation (NFE2L2) in macrophages from severe COVID-19 cases indicates a metabolic reprogramming that supports their inflammatory function." (PMID 39928675, 2025). "NFE2L2 expression in neutrophils was significantly higher in COVID-19 patients compared to the healthy controls." (PMID 39928675, 2025). "Nuclear factor, erythroid 2-like 2 (NFE2L2) expression is markedly increased in NK cells from patients with severe COVID-19, indicating its role in influencing NK cell activity and antiviral responses, likely reflecting an attempt to mitigate oxidative stress and inflammation." (PMID 39928675, 2025). "Serum from patients with severe COVID-19 significantly upregulated genes involved in the cellular antioxidant response in HUVEC, including NFE2L2, HMOX1, SOD1, CAT, GPX1, and GSR." (PMID 41583455, 2025). "There are no previous reports associating this polymorphism with COVID-19; however, NFE2L2 polymorphisms may modulate the expression of the transcription factor or affect its ability to translocate into the nucleus and bind to the ARE site in target gene promoters." (PMID 36613859, 2022). "Our results constitute one of the first pieces of evidence of the relationship of NFE2L2 (rs2364723C/G) and KEAP1 (rs9676881A/G; rs34197572C/T) with COVID-19." (PMID 36613859, 2022). "Furthermore, the role of NFE2L2 (Nuclear Factor, Erythroid 2-Like 2), commonly known as NRF2, adds another dimension to understanding the oxidative stress response in severe COVID-19 cases." (PMID 39928675, 2025). "Moreover, we identified that more than half of the Mon IFI30 marker peaks were shared with monocytes from infants affected with COVID-19, and BACH1, NFE2L2, FOS, and FOSL2 are the master regulators of the cell state." (PMID 39712003, 2024). "Our results showed that NFE2L2 rs2364723C>G allele G had a protective effect against severe COVID-19, while KEAP1 rs9676881A>G allele G and rs34197572C>T minor allele T were associated with more aggressive stages of COVID-19." (PMID 36613859, 2022).
diabetic nephropathy (18 papers, 2013 to 2025). "An ongoing phase 2/3 clinical trial is also evaluating the interaction between the rs35652124 polymorphism in the NFE2L2 gene and curcumin supplementation on Nrf2 expression, oxidative stress, and renal function in early diabetic nephropathy patients (NCT03262363)." (PMID 33396350, 2020). "Downregulation of NFE2L2 was observed in kidneys tissues of diabetic mice, with upregulation of NFE2L2 shown to inhibit ferroptosis and delay the progression of diabetic nephropathy." (PMID 35992146, 2022). "Although changes in NFE2L2 nuclear expression in podocytes between normal and diseased kidneys were not statistically significant, there was a slight upward trend in the distribution in diabetic nephropathy and mesangial IgA groups." (PMID 37681897, 2023). "Furthermore, pharmacological activation of Nfe2l2 in the streptozotocin (STZ) diabetic mouse model has been shown to attenuate the characteristics of diabetic nephropathy, including reduced albuminuria, renal hypertrophy and thickening of the basement membrane." (PMID 37681897, 2023). "The response shown by the antioxidants to the signalling pathways NFE2L2 and NFE1-NFE2L2/ARE is considered a promising target against diabetic complications affecting the pulmonary, hepatic, digestive, neural, and cardiovascular systems as well as diabetic nephropathy." (PMID 33299532, 2020).
melanoma (18 papers, 2013 to 2025). A malignant, usually aggressive tumor composed of atypical, neoplastic melanocytes. "Based on initial studies, NRF2 was first considered a tumor suppressor gene, since a number of studies in other cancer types (i.e., colon, melanoma) and in mice showed that NFE2L2 deficiency increases the susceptibility to cancer." (PMID 34440648, 2021). "In a study addressing the function of the transcription factor Nuclear Factor Erythroid 2 Like 2 (NFE2L2 or more common NRF2) in melanoma, we observed that EGFR is strongly reduced after NRF2 knockdown." (PMID 33916908, 2021). "To get insight into further processes affected by NRF2, we performed RNA sequencing of UACC-62 melanoma cells transfected with control or NFE2L2-specific siRNA (N2)." (PMID 32978520, 2020). "To investigate whether there is a connection between the expression of NRF1, NFE2L2 and ATGs, we analysed existing microarray data and investigated the gene expression profiles of 18 benign nevi and 45 primary melanoma tissue samples." (PMID 34458153, 2021). "We performed a siRNA-mediated knockdown of NRF1 and NFE2L2 in melanoma cells." (PMID 34458153, 2021). "Recent studies suggested that aldo-keto reductases (AKRs), a superfamily of NADPH-linked oxidoreductases, including AKR1C1, AKR1C2, and AKR1C3, are potential NFE2L2 target genes responsible for ferroptosis resistance via inhibiting lipid peroxidation in melanoma cells." (PMID 34938739, 2021). "Since our previously published and current data show decreased expression of three of the core ATGs (ATG5, ATG7 and Beclin-1) in melanoma, we decided to study the impact of NRF1 and NFE2L2 on the expression of these ATGs." (PMID 34458153, 2021). "The positive effect of NRF2 on EGFR levels was confirmed in two independent EGFR-positive melanoma cell lines, where the extent of EGFR reduction notably correlated with the efficiency of the NFE2L2 knockdown." (PMID 33916908, 2021). "Indeed, knockdown of NFE2L2 decreased the expression of ATGs but had no impact on the migration potential of melanoma cells." (PMID 34458153, 2021). "Additionally, NF-E2-related factor 2 (NFE2L2, commonly NRF2), a master transcription factor that regulates several cytoprotective genes in response to oxidative and electrophilic stress, plays a protective role in melanocytes and melanoma cells, in which high levels of ROS are produced." (PMID 39858507, 2025).
Sepsis (18 papers, 2013 to 2025). Sepsis is defined as life-threatening organ dysfunction caused by a dysregulated host response to infection. "This study is the first examining, the association of common variants of NFE2L2 gene with susceptibility to ARDS among patients with severe sepsis, finding an association of 10 SNPs with this syndrome." (PMID 26077880, 2015). "In the present study, we aimed to assess the association of common genetic variants in NFE2L2 with ARDS in patients admitted with severe sepsis in a Spanish network of post-surgical and critical care units." (PMID 26077880, 2015). "The purpose of this study was to investigate whether common variants across the nuclear factor erythroid 2-like 2 (NFE2L2) gene contribute to the development of the acute respiratory distress syndrome (ARDS) in patients with severe sepsis." (PMID 26077880, 2015). "Because we found renal oxidative stress to be prominent in response to sepsis we also probed for NFE2L2, a transcription factor important in the anti-oxidant response, and found that it too was increased in the nuclear compartment during sepsis at 24 hours." (PMID 24988481, 2014). "Third, the use of population-based controls instead of at-risk controls precludes deducing whether the NFE2L2 gene is associated with ARDS or with the underlying condition (e.g., severe sepsis)." (PMID 26077880, 2015).
prostate carcinoma (17 papers, 2010 to 2026). A carcinoma that arises from epithelial cells of the prostate gland. "In addition, survival analysis stratified by cancer type revealed that NFE2L2 MU was associated with shorter OS in prostate cancer (HR: 3.02, 95% CI 1.25–7.30) and NSCLC (HR: 1.57, 95% CI 1.28–1.94), while contrary association in endometrial cancer (HR: 0.27, 95% CI 0.13–0.58)." (PMID 37794491, 2023). "NFE2L2 mutation causes several types of cancer such as esophageal squamous cell carcinoma, lung squamous cell carcinoma (LUSC), head and neck cancer, prostate cancer, hepatocellular cancer, oral cancer, brain lower grade glioma, and bladder cancer." (PMID 37794491, 2023). "Z-Ligustilide extracted from Angelica sinensis can inhibit the growth of mouse prostate cancer cells by demethylation of the promoter of the tumor suppressor gene NFE2 Like BZIP Transcription Factor 2 (NrF2)." (PMID 35774614, 2022). "NFE2L2 expression is down-regulated in prostate cancer and suppression of NFE2L2 promotes prostate tumor development in TRAMP mice." (PMID 20070897, 2010). "Additionally, complementary studies in TRAMP-C1 prostate cancer models confirm NFE2L2 reactivation using DNMT inhibitor 5-aza-2′-deoxycytidine and histone deacetylase inhibitor Trichostatin A." (PMID 40868167, 2025). "Clinical analyses of 27 prostate cancer specimens and LNCaP cells via MAQMA and bisulfite sequencing identified three hypermethylated NFE2L2 promoter CpG sites that suppress transcriptional activity." (PMID 40868167, 2025).